LEP (leptin)
Diseases named in the same sentence as LEP in open-access papers (continued):
Sharing a sentence is not in itself a finding about the gene and the disease.
gastric cancer (continued). "A recent study showed that the concentration of serum leptin, which is related to the progression and angiogenesis of gastric cancer and predicts poorer prognostic outcomes, was significantly higher in Mongolians than in Han Chinese(3·58 ± 1·85 ng/ml and 3·02 ± 1·75 ng/ml, respectively, P = 0·049)." (PMID 35719924, 2022). "Higher leptin expression was found in advanced gastric cancer and proximal tumour locations." (PMID 34827598, 2021). "In 38 samples from patients with gastric adenoma (GA), early gastric cancer (EGC), and advanced gastric cancer (AGC) assessed by immunostaining for leptin and ObR expression, leptin was expressed in >40%, while ObR expression showed a stage-related progressive increase from 2.6% to 18.4%." (PMID 33334030, 2020). "Immunohistochemistry for leptin signalling-related proteins (leptin, leptin-receptor, pSTAT3, ERK, pAkt, mTOR and HIF-1 alpha), and in situ hybridization for EBV-encoded small RNAs was performed in 343 cases of gastric carcinomas." (PMID 26147886, 2015). "The present study indicated that leptin signaling proteins may contribute to HIF-1 alpha-mediated angiogenesis in gastric carcinoma." (PMID 26147886, 2015). "Case–control studies have reported lower serum leptin levels in gastric cancer patients compared to controls but these studies did not provide data on the association between leptin levels and gastric cancer risk and did not examine leptin and gastric cancer subsite." (PMID 37455285, 2023). "Leptin increases the expression of matrix metalloproteinases, which degrade ECM components, thereby affecting gastric cancer invasion." (PMID 38255203, 2024). "Leptin promoted STAT3 and ERK 1/2 activation in the AGS, SNU-484, SNU-601, and SNU-638 gastric cancer cell lines." (PMID 33334030, 2020). "We found that immune related genes such as TLR8, Interleukin-7 (IL-7), Leptin (LEP), IL1RN had intimate relationships with AQP9 expression in breast, colon, lung and gastric cancers." (PMID 33247170, 2020). "We investigated the clinicopathological implications of leptin-signaling proteins and Epstein-Barr virus (EBV)-infection status in gastric carcinomas." (PMID 26147886, 2015). "In conclusion, leptin-signaling proteins and EBV status show different significance on patient survival, according to subsets of gastric carcinomas." (PMID 26147886, 2015). "In conclusion, leptin signaling-related proteins and EBV status show different significance on patient survival according to subsets of gastric carcinoma." (PMID 26147886, 2015). "Further studies are required to understand how leptin signaling-related proteins and the EBV status play a role in regulating carcinogenesis, and ultimately to establish them as therapeutic targets in gastric carcinomas." (PMID 26147886, 2015). "A decrease in leptin levels after gastrectomy was also reported in gastric cancer patients, although the control group with non-surgical treatment was limited." (PMID 34501456, 2021). "Few studies about gastric cancer have reported a comparison between cachectic and non-cachectic patients regarding leptin serum level." (PMID 32660156, 2020). "We evaluated expression of leptin-signaling-related proteins (leptin, leptin-receptor, pSTAT3, ERK, pAkt, mTOR and HIF-1 alpha) and the EBV infection status within cancer cells, and determined their clinicopathological significance in gastric carcinomas." (PMID 26147886, 2015). "EBV-positive may have a limited prognostic value only in the advanced gastric cancer group, and leptin signaling may not be involved in EBV-positive gastric carcinogenesis." (PMID 26147886, 2015).
generalized lipodystrophy (35 papers, 2016 to 2025). Almost complete absence of subcutaneous and/or visceral adipose tissue. "Metreleptin is a leptin analog used to treat patients with congenital generalized lipodystrophy in leptin-deficient patients with mutations in the leptin gene." (PMID 37375686, 2023). "In this study, we used leptin-deficient obese and generalized lipodystrophy mice and rats, respectively, as fatty liver models." (PMID 35013417, 2022). "Currently, it has been approved for generalized lipodystrophy, but its effects are potentially valuable for patients with other conditions associated with low, normal, or high levels of leptin serum." (PMID 35027962, 2021). "A leptin analog is a hormone approved in the United States to treat congenital leptin deficiency and generalized lipodystrophy." (PMID 35027962, 2021). "Leptin replacement therapy is necessary in patients with homozygous Lep mutations or acquired leptin dysfunction that produces congenital and acquired generalized lipodystrophy." (PMID 27055280, 2016). "Among the treatments that could be considered for future treatment is the usage of metreleptin, a recombinant analog of human leptin, which has been approved for the treatment of generalized lipodystrophy, a rare metabolic disorder characterized by the loss of adipose tissue." (PMID 38542117, 2024). "Leptin therapy has been a significant breakthrough for generalized lipodystrophy treatment; however, more effective treatments are still needed for partial and acquired forms." (PMID 40892266, 2025). "Importantly, AS can resume leptin secretion after deprivation of adipogenic stimulus, indicating that they are suitable for implantation in animals and potentially sustain leptin production in mouse models of generalized lipodystrophy or genetic leptin deficiency." (PMID 37024989, 2023). "Serum leptin levels, which are strongly correlated with total body fat mass, were very low (1.9 ng/mL) and similar to those usually reported in generalized lipodystrophy, further confirming the lipoatrophic phenotype." (PMID 35341481, 2022). "Leptin replacement therapy is currently the gold standard therapeutic treatment for generalized lipodystrophy." (PMID 36320417, 2022). "Leptin, one of the most thoroughly investigated adipokines, is referred to in the next section in congenital generalized lipodystrophy." (PMID 32056035, 2020). "Recent reports have emphasized the concept that leptin has insulin-sensitizing effects, as it was demonstrated in patients affected with congenital generalized lipodystrophy and in mice treated with leptin sensitizers such as celastrol." (PMID 28626772, 2017). "Recombinant leptin therapy is very effective in patients with generalized lipodystrophy and to a lesser extent in other forms of partial lipodystrophy, but leptin levels in most patients with FPLD1 are well above current thresholds (4 to 10 μg/L) for leptin therapy." (PMID 28973478, 2017). "However, recombinant leptin may not be as effective in patients with FPLD compared to patients with generalized lipodystrophy, given that the former have significantly higher concentrations of leptin." (PMID 35920656, 2022). "The clinical diagnosis of partial lipodystrophy, rather than generalized lipodystrophy, was based on the loss of adipose tissue mainly in the extremities and the leptin levels (27.7 ng/ml; normal range 3.7–11.1 ng/ml), which indicates the presence of significant amounts of functional adipose tissue." (PMID 30319454, 2018). "Metreleptin, a recombinant analog of human leptin, has been approved by the European Medicines Agency (EMA), not only for generalized lipodystrophy but also for partial lipodystrophy patients >12 years of age when standard treatments have failed." (PMID 39113684, 2024). "Metreleptin is a leptin replacement therapy that was FDA-approved in 2014 as an adjunct to diet, which was developed specifically for treating patients with generalized lipodystrophy." (PMID 37937009, 2023).
generalized lipodystrophy (continued). "Leptin deficiency can result from congenital generalized lipodystrophy (CGL) and congenital leptin deficiency (CLD), in which leptin’s biological actions are absent because of a mutation in the leptin gene." (PMID 40415699, 2025). "In individuals with generalized lipodystrophy, leptin levels are typically very low or absent due to the lack of adipose tissue." (PMID 38715796, 2024). "A lack of leptin contributes to congenital/acquired generalized lipodystrophy, making leptin an ideal direct drug target for this scenario in particular." (PMID 37937009, 2023). "Thus, absence of leptin and adiponectin, particularly when combined, contributes to the osteosclerotic phenotype of congenital generalized lipodystrophy." (PMID 31233501, 2019).
colitis (33 papers, 2010 to 2025). Inflammation of the colon. "Previous studies have demonstrated that leptin-deficient ob/ob mice exhibit protection against dextran sulfate sodium (DSS)-induced colitis, whereas administration of leptin renders these mice susceptible to the disease." (PMID 40809439, 2025). "High serum leptin levels were shown to be associated with acute inflammation in a colitis animal model, and increased serum leptin concentrations have been observed in IBD patients compared with those in healthy controls." (PMID 35888062, 2022). "Leptin-deficient mice were also protected from DSS-induced colitis and leptin administration reversed disease susceptibility." (PMID 32102231, 2020). "Overall, colitis induces a decrease in the levels of the mRNAs encoding leptin and adiponectin in MAT but an increase in the levels of mRNAs encoding inflammatory markers." (PMID 33167521, 2020). "In an in vivo study using an oxazolone-induced colitis model, leptin-deficient ob/ob mice were protected from colitis by suppressing expression of the key transcription factors such as T-bet and GATA-3 under Th1 and Th2 polarization." (PMID 33334069, 2020). "In our own work, we were able to demonstrate that leptin-deficient ob/ob mice are protected from DSS-induced colitis and that leptin administration reverses disease susceptibility in mice." (PMID 30369924, 2018). "As in our work, the authors observed increased leptin expression in the fatty tissue of animals with colitis associated with HFD." (PMID 22073943, 2011). "The protective effects of HFD feeding against experimental colitis might in part be associated with the role of leptin in IEC apoptosis." (PMID 35888062, 2022). "Therefore, in this study, we aimed to elucidate the effect of dietary fat content on colitis development in association with serum leptin signaling and gut-microbiota composition." (PMID 35888062, 2022). "A similar study with sitagliptin in leptin-deficient mice, in which intestinal carcinogenesis was initiated using 1,2-dimethylhydrazine together with chemically induced colitis, reported a lower number of aberrant crypt foci and lower intestinal IL6 expression." (PMID 35565202, 2022). "In addition, the plasma concentration of leptin was increased in several experimental animal models of colitis such as TNBS-mediated colitis and indomethacin-induced ileitis, and was associated with disease severity." (PMID 33334069, 2020). "In an in vivo IL-10-deficient mouse model, treatment with a pegylated leptin antagonist resulted in attenuation of the clinical colitis score, a reversal of colitis-associated pathogenesis suppression of systemic and mucosal inflammatory cytokine production, and an increase in mucosal Treg cells." (PMID 33334069, 2020). "Overall, these results demonstrated that LEP possessed pronounced anti-colitis capacity and its mechanism might be tightly associated with protecting intestinal mucosal barrier function, suppressing inflammatory response, ER stress, and oxido-nitrosative stress." (PMID 33981232, 2021). "Adiponectin was found to have a positive effect on reducing ICI-induced colitis in mice models, while lower circulating leptin levels were found in patients with irAEs that received anti-PD-1 antibodies." (PMID 41010821, 2025). "In the current study, it was found that plasma leptin concentrations were elevated in patients with TNBS-induced colitis and indomethacin-induced ileitis, and these levels correlated with disease severity." (PMID 40809439, 2025). "A particularly noteworthy observation was the significant reduction in plasma leptin levels following IAP treatment in obese mice with colitis." (PMID 38255781, 2024). "Our study remains in keeping with these findings since we noticed a prominent increase in plasma leptin levels in obese mice with colitis, but this effect was reversed in exercising mice concomitantly treated with IAP." (PMID 35328382, 2022).
colitis (continued). "High concentrations of leptin with excess adiposity aggravate colonic inflammation in animals with colitis, whereas elevated leptin levels show a protective effect against inflammation by modulating mucin secretion in intestinal cells." (PMID 35888062, 2022). "Thus, our data indicate that HFD feeding alleviated DSS-induced colitis symptoms and colonic mucosal damage by reinforcing colonic barrier function and ameliorating immune responses, which might in part be associated with the protective role of leptin in IEC." (PMID 35888062, 2022). "Leptin level significantly increased in the plasma of obese mice with colitis compared to obese sedentary mice." (PMID 35328382, 2022). "Strikingly, T-cells isolated from db/db mice delayed the development of colitis, indicating that the leptin/LepR axis is required for colitis progression by activating the T lymphocytes." (PMID 33935782, 2021). "In the sedentary SD group of mice with TNBS-induced colitis, the overexpression of mRNA for leptin was observed as compared to the sedentary animals fed an SD without colitis (p < 0.05)." (PMID 33557311, 2021). "Meanwhile, the ER stress markers IRE1α and XBP1 were evidently elevated, whereas Bip, ATF6, PERK, CHOP, and C-Cas3 were descended in the LEP treatment group as compared with that in the DSS-induced colitis group." (PMID 33981232, 2021). "In vivo, the addition of a β3 receptor agonist or a cholecystokinin-B receptor antagonist results in a reduction of leptin secretion and colonic damage during the early stages of colitis." (PMID 33159578, 2021). "In experimental colitis, exogenous leptin has been shown to have an anti-inflammatory function being able to inhibit tissue infiltration of neutrophils and thus protecting the colonic tissue from damage." (PMID 33159578, 2021). "In contrast to the proinflammatory role of leptin, adiponectin maintains intestinal homeostasis and protects against murine colitis through interactions with its receptor AdipoR1 and by modulating adaptive immunity." (PMID 33167521, 2020). "In mice, intra-rectal administration of leptin results in NF-κB-mediated colitis with epithelial monolayer damage and neutrophil activation." (PMID 31234447, 2019). "In fact, the development of colitis was significantly delayed using this approach, indicating that the stimulatory effect of leptin plays a crucial role in this model." (PMID 30369924, 2018). "In an early study, systemic leptin concentrations were determined during the course of acute experimental colitis." (PMID 30369924, 2018). "In this study, the concentration of leptin in the plasma increased in TNBS-induced colitis and indomethacin-induced ileitis and correlated with disease severity." (PMID 30369924, 2018). "Recent data indicate that the administration of a pegylated leptin antagonist (PG-MLA) was sufficient to protect from chronic experimental colitis." (PMID 30369924, 2018). "Our present study is in keeping with the previous findings on leptin expressed in mWAT in rodents with experimental colitis and in CD patients." (PMID 28425943, 2017). "The importance of the leptin derived from abdominal fat for the pathogenesis of colitis is supported by an observation that treatment with a leptin antagonist ameliorated the development of chronic experimental colitis." (PMID 28425943, 2017). "The plasma leptin levels were significantly decreased in the mice with TNBS colitis subjected to voluntary exercise as compared to the values obtained in the group of TNBS mice fed a HFD without voluntary exercise (p < 0.05)." (PMID 28425943, 2017). "In one study, leptin was found to have an anti-inflammatory effect in experimental colitis; in another study it was shown that leptin replacement restored impaired endothelial cell function." (PMID 27800222, 2015).